CABP2 (calcium binding protein 2)
Description:
Required for sound encoding at inner hair cells (IHCs) synapses, likely via inhibition of the inactivation of voltage-gated calcium channel of type 1.3 (Cav1.3) in the IHCs. Required for the normal transfer of light signals through the retina (By similarity).
Synonyms: DFNB93
Tractability: Antibody: UniProt places it where antibodies can reach, with high confidence; its Gene Ontology location is reachable by antibodies, with high confidence.
Gene: Protein-coding gene on chromosome 11 (67,518,912 to 67,524,517, reverse strand). Ensembl gene ENSG00000167791.
Subcellular location: Cytoplasm, perinuclear region; Cell membrane; Golgi apparatus
Pathways (Reactome):
Sensory Perception: Sensory processing of sound by inner hair cells of the cochlea
Gene Ontology:
Molecular function: protein binding; calcium channel regulator activity; calcium ion binding
Biological process: phototransduction; sensory perception of sound; signal transduction; visual perception
Cellular component: Golgi apparatus; plasma membrane; perinuclear region of cytoplasm
Genetic constraint (gnomAD): Loss-of-function variants: 25 observed, 26.88 expected, observed/expected ratio (o/e) 0.93, 90% interval 0.68 to 1.3. The upper end of that interval is the gene's LOEUF score, 1.3, which puts it in group 5 of 6, group 1 being the genes least tolerant of losing a copy. Missense variants: 310 observed, 301.29 expected, observed/expected ratio (o/e) 1.03, 90% interval 0.94 to 1.13. Synonymous variants: 138 observed, 119.3 expected, observed/expected ratio (o/e) 1.16, 90% interval 1.01 to 1.33.
Gene-disease validity (ClinGen):
ClinGen rates the evidence that CABP2 causes each of these diseases.
nonsyndromic genetic hearing loss (autosomal recessive): Definitive.
Homologues: Orthologues: macaque CABP2 (97% identical), pig CABP2 (91% identical), dog CABP2 (89% identical), guinea pig CABP2 (89% identical), mouse Cabp2 (88% identical), rat Cabp2 (85% identical), chimpanzee CABP2 (71% identical), zebrafish cabp4 (44% identical), Caenorhabditis elegans cal-1 (28% identical), Caenorhabditis elegans cal-3 (27% identical), Caenorhabditis elegans E02A10.3 (26% identical), Caenorhabditis elegans K03A1.4 (24% identical), and 9 more. Paralogues in human: CABP1 (56% identical), CABP4 (55% identical), CABP5 (51% identical), CALML3 (31% identical), CALM1 (30% identical), CALM2 (30% identical), CALM3 (30% identical), CALN1 (30% identical), CABP7 (30% identical), CETN1 (28% identical), CETN2 (27% identical), CETN3 (24% identical), and 8 more.
Diseases named in the same sentence as CABP2 in open-access papers:
CABP2 is named in the same sentence as 10 diseases in open-access papers, as found by Europe PMC text mining. Sharing a sentence is not in itself a finding about the gene and the disease. The quoted sentences say what the papers report.
Hearing impairment (9 papers, 2016 to 2025). A decreased magnitude of the sensory perception of sound. "In anticipation of clinical trials, we developed and released a registry for CABP2‐associated hearing impairment." (PMID 40927552, 2025). "To date, nearly two dozen patients with CABP2‐associated hearing impairment have been published, the majority of whom report moderate to severe hearing impairment." (PMID 40927552, 2025). "Given the rarity of CABP2‐associated hearing loss and its considerable therapeutic potential, we established the CABP2 Registry (Clinical Trials Identifier: NCT06680934) as a centralized platform for patient data collection." (PMID 40927552, 2025). "This article reviews preclinical gene replacement strategies for the treatment of hereditary hearing loss, touches on the criteria of a good therapeutic target, and outlines qualities of CABP2 that make it an excellent therapeutic target." (PMID 40927552, 2025). "Yet, the loss of CaBP2 alone still results in progressive hearing impairment in mice and DFNB93 in humans." (PMID 39718549, 2024). "Mutations in human CABP2 associated with the autosomal recessive locus DFNB93 result in hearing loss, underlining its functional importance." (PMID 36598134, 2023). "We report two Finnish families with hearing impairment due to the CABP2 splice site variant c.637+1G>T." (PMID 35150090, 2022). "A mutation in the Cabp2 gene is associated with hearing impairment in humans, likely through dysregulation of the Cav1.3 channels present in auditory inner hair cells, which are modulated by CaBP2." (PMID 27822497, 2016). "The only unfavorable factor so far is the rarity of CABP2‐associated hearing impairment, which may be due to incomplete reporting and can thus be addressed with a patient registry." (PMID 40927552, 2025). "Biallelic variants in CABP2 are associated with non‐syndromic hearing loss (DFNB93)." (PMID 40927552, 2025). "Taken together, our results support a role for CaBP2 as a likely modulator of Cav1.3 channels in inner and outer hair cells, which may account for hearing impairment associated with DFNB93." (PMID 26809054, 2016). "The first preclinical therapy of Cabp2‐associated hearing impairment used AAV2/1 and AAV‐PHP.eB vectors to deliver Cabp2 coding sequence into the cochleae of P5‐7 Cabp2−/− mice." (PMID 40927552, 2025). "Deletion of CaBP2 results in an early-onset, progressive hearing impairment in the KO mouse model and moderate to severe hearing impairment, DFNB93, in affected human patients." (PMID 39718549, 2024). "Homozygous missense variants in RDX (OMIM 179410), CABP2 (OMIM 607314), and ESRRB (OMIM 602167) were found to contribute to hearing loss in three individuals." (PMID 32681043, 2020). "Based on disease modeling in Cabp2–/– mice, DFNB93 hearing impairment has been ascribed to enhanced steady-state inactivation of IHC CaV1.3 channels, effectively limiting their availability to trigger synaptic transmission." (PMID 34489639, 2021).
autosomal recessive hearing loss (3 papers, 2022 to 2025). "Clinically relevant mutations in CaBPs are associated with a range of pathogenic phenotypes, including autosomal recessive hearing loss caused by mutations in CaBP2, as well as various visual disorders, dystrophies, and frontal lobe epilepsy linked to CaBP4 mutations." (PMID 39936944, 2025). "Mutations in the CABP2 gene underlie non-syndromic autosomal recessive hearing loss DFNB93." (PMID 39718549, 2024). "Furthermore, many CaBP2 mutations are linked to autosomal recessive hearing loss." (PMID 39936944, 2025).
infection (1 paper, 2011). The state of being infected such as from the introduction of a foreign agent such as serum, vaccine, antigenic substance or organism. "In this case, even when transfected individually, each of the four siRNA duplexes was able to silence the CABP2 gene in host cells, resulting in a reduced infection by T. cruzi parasites in comparison to scrambled siRNA-transfected cells." (PMID 21625474, 2011).
CABP2 also shares sentences with these, for which no sentence is quoted: deafness (4 papers); connective tissue disorder (1); frontal lobe epilepsy (1); hearing disorder (1); nonsyndromic deafness (1); retinal degeneration (1); visual disorders (1).